RNU7-173P (RNA, U7 small nuclear 173 pseudogene)
Gene: Small nuclear RNA gene on chromosome 20 (47,826,969 to 47,827,044, reverse strand). Ensembl gene ENSG00000238950.
Homologues: Orthologues: chimpanzee U7 (99% identical), dog U7 (62% identical). Paralogues in human: RNU7-92P (97% identical), RNU7-144P (87% identical), RNU7-157P (64% identical), RNU7-104P (63% identical), RNU7-65P (62% identical), RNU7-79P (62% identical), RNU7-80P (62% identical), RNU7-9P (62% identical), RNU7-11P (61% identical), RNU7-127P (61% identical), RNU7-134P (61% identical), RNU7-13P (61% identical), and 141 more.